ATG7 (autophagy related 7)
Diseases named in the same sentence as ATG7 in open-access papers (continued):
Sharing a sentence is not in itself a finding about the gene and the disease.
Insulin resistance (continued). "The mRNA expression of NF-κB, AKT, ATG7, and FGF21 in the liver tissue was analyzed to confirm the effects of MGF on the linkage of autophagy and insulin resistance, and the current results explained that MGF decreased inflammation and regulated autophagy." (PMID 36499655, 2022). "Reversely, hepatic overexpression of Atg7 in HFD-fed mice improved fatty liver and insulin resistance." (PMID 28452943, 2017). "Furthermore, PGE1 combined with ATG7 siRNA showed no additive effects on these indexes above of insulin resistance." (PMID 29311680, 2018). "Contrary to the results of beta cell-specific Atg7-knockout (Atg7Δβcell) mice, standard diet-fed AAV-shAtg7 mice (STD + AAV-shAtg7) did not demonstrate hyperglycaemia, glucose intolerance, nor insulin resistance." (PMID 29180700, 2017).
non-small cell lung carcinoma (29 papers, 2012 to 2026). A group of at least three distinct histological types of lung cancer, including non-small cell squamous cell carcinoma, adenocarcinoma, and large cell carcinoma. "The autophagic dependence of Ras-driven non-small lung cell carcinoma cells has been confirmed using Atg7-deficient cells." (PMID 40723786, 2025). "A non-small-cell lung cancer model deficient in ATG7 was shown to transition to an oncocytic phenotype characterized by mitochondrial accumulation." (PMID 40806782, 2025). "In genetically engineered mouse models (GEMMs) the deletion of essential Atg7 is associated with KRAS-driven non-small-cell lung cancer (NSCLC)." (PMID 33802014, 2021). "Previous studies have shown that CSNK1A1 inhibits the growth of non-small cell lung cancer by inducing autophagy through the AKT/FOXO3a/ATG7 pathway." (PMID 41213929, 2025). "FOXO3a-transactivated ATG7 acts as a tumor suppressor in non-small cell lung cancer (NSCLC) and mediates CK1α-induced autophagy, an anti-neoplastic mechanism." (PMID 38553562, 2024). "This role for autophagy in cancer can be established through the deletion of Atg7 in a spontaneous KRasG12D-driven non-small cell lung cancer (NSCLC) GEM model." (PMID 38067169, 2023). "For example, casein kinase 1 alpha 1 activates PTEN/AKT/FOXO3A/ATG7 axis-mediated autophagy, inhibiting the growth of non-small cell lung cancer." (PMID 36016573, 2022). "The m6A methyltransferase METTL13 positively regulates autophagic flux by upregulating the expression of LC3B, ATG5, and ATG7 and plays a key role in β-elemene reversal of gefitinib resistance in non-small cell lung cancer." (PMID 36263177, 2022). "Acute ATG7 ablation in mice with preexisting non-small cell lung cancer suppressed tumor growth via shutting off the mammalian target of rapamycin and mitogen-activated protein kinase signaling." (PMID 32139670, 2020). "Atg7 was deleted concurrently with KRas G12D activation in mouse models for non-small cell lung cancer." (PMID 30782064, 2019). "In this regard, in a Kras-driven non-small cell lung cancer (NSCLC) mouse model with a concurrent deletion of Atg7 to inhibit autophagy in the tumors, the authors found a decrease in tumor growth with accumulation of defective mitochondria." (PMID 30622432, 2018). "Moreover, ATG7, a gene involved in autophagy, is regulated by FOXO3a in non-small cell lung cancer cells." (PMID 38421826, 2024). "For example, FOXO3-induced transcription of ATG7 promote autophagy in non-small-cell lung cancer." (PMID 35338124, 2022). "However, the overexpression of CK1α has been shown to convectively activate autophagic flux in non-small cell lung cancer (NSCLC) through the PTEN/AKT/FOXO3A/ATG7 axis." (PMID 33330516, 2020). "Thus, ATG7 deletion in a K-ras-driven non-small cell lung cancer (NSCLC) significantly reduces tumor growth." (PMID 29783720, 2018). "For example, the fifth ranked regulator MYC was recently proved to mitigate its oncogenic activity by chaperone-mediated autophagy (CMA) regulation and the ninth ranked regulator XIST was determined to increase autophagy activity in non-small-cell lung cancer by regulation of ATG7." (PMID 30400235, 2018). "In a KRas-dependent model of spontaneous non-small-cell lung cancer (NSCLC), the inhibition of autophagy through ATG7 decreased tumor growth, converting adenomas and carcinomas into a benign disease characterized by the accumulation of defective mitochondria." (PMID 35745567, 2022). "In non-small-cell lung cancer (NSCLC), casein kinase 1 alpha (CK1α), an autophagy inducer, activates the PTEN/AKT/FOXO3a/ATG7 axis, which increases autophagy and suppresses tumor progression to negatively regulate tumor growth." (PMID 34895252, 2021). "Upregulation of GATA6, a transcription factor that mediates the expression of autophagy-related genes such as ATG5, ATG7, and ATG12 by erlotinib treatment promotes treatment resistance in cellular models of non-small cell lung cancer (NSCLC)." (PMID 32245178, 2020).
non-small cell lung carcinoma (continued). "Another study showed that CSNK1A1 inhibits the growth of non-small cell lung cancer by inducing autophagy via the AKT/FOXO3a/ATG7 pathway without affecting mTOR activity." (PMID 41213929, 2025). "Therefore, in non-small cell lung cancer, it can inhibit the activeness of HSF1 and PSMD10 in the ATG7 promoter, thus inhibiting ATG7 transcription." (PMID 38243168, 2024). "PTEN regulates autophagy in PTEN/AKT/FOXO3a/ATG7 axis in non-small-cell lung cancer (NSCLC) cells, independent of mTOR and Beclin-1." (PMID 33344463, 2020). "In non-small cell lung cancer cell line models, GX15-070-induced Atg7-dependent autophagy independent of Beclin 1 and Bax/Bak." (PMID 22240779, 2012).
myocardial infarction (23 papers, 2017 to 2026). Gross necrosis of the myocardium, as a result of interruption of the blood supply to the area, as in coronary thrombosis. "Nineteen DNA sequence variants (DSVs) containing single-nucleotide polymorphisms (SNPs) have been observed in the Atg7 gene promoter of coronary artery disease patients, including those with acute myocardial infarction (AMI)." (PMID 38553562, 2024). "Studies have shown that variants of the ATG7 gene are related to some diseases, such as sporadic Parkinson’s disease, systemic lupus erythematous, acute myocardial infarction, and primary ovarian insufficiency." (PMID 31749688, 2019). "Our results demonstrated that ATG7 knockdown reversed the elevated autophagy levels observed in the hearts of METTL3-CKO mice following myocardial infarction." (PMID 39893158, 2025). "Evidence suggests that miR-188 can help reduce the severity of myocardial infarction by inhibiting the autophagic process through the ATG7 protein." (PMID 37736510, 2023). "As ADSC-derived exosomes have been studied and applied in much research, miR-188-3p has been found to target ATG7 and inhibit autophagy and apoptosis during myocardial infarction." (PMID 33717653, 2021). "The APF lncRNA act as a ceRNA by antagonizing miR-188-3p to increase ATG7 expression, thus affect autophagy and myocardial infarction." (PMID 34868083, 2021). "APF knockdown can attenuate cardiomyocyte autophagy and reduce myocardial infarction sizes in response to a I/R injury by targeting the miR-188-3p/ATG7 axis." (PMID 33884101, 2021). "LncRNA autophagy promoting factor (APF) was indicated to sponge miR-188-3p directly targeting ATG7 to modulate autophagy and myocardial infarction." (PMID 34022925, 2021). "A study of cardiovascular diseases reveals that miR-188-3p suppresses autophagy and myocardial infarction by targeting ATG7." (PMID 33953792, 2021). "miR-188-3p suppresses autophagy and myocardial infarction by targeting ATG7, While myocardial infarction is promoted by miR-325 regulated autophagic cell death." (PMID 28362341, 2017). "In the mouse model of myocardial infarction, overexpression of miR-188-3p attenuates autophagy and infarct size through targeting autophagy mediator ATG7." (PMID 28362341, 2017). "We found that in mice with myocardial infarction, overexpression of ATG7 could improve cardiac function to some extent, although the reduction in myocardial fibrosis area was slight and not statistically significant." (PMID 39893158, 2025). "In compliance with these results, in rats with myocardial infarction, the treatment of adipose-derived stromal cells-derived exosomes containing miR-93-5p showed a protective effect in rats with myocardial infarction, targeting Atg7 and Toll-like receptor 4 (TLR4)." (PMID 33573156, 2021). "LncRNA APF could control the expression of miR-188-3p, which suppressed myocardial infarction and autophagy by targeting ATG7." (PMID 30103699, 2018). "Similarly, miR-188-3p regulates autophagy and myocardial infarction by altering Atg7 expression." (PMID 38553562, 2024). "It was reported that myocardial infarction could induce increased ATG7 expression." (PMID 30945454, 2019). "Thus, the APF/miR-188-3p/ATG7 axis plays a key role in regulating autophagic cell death in cardiovascular tissues; moreover, it may be a potential target for novel therapeutic strategies for treating myocardial infarctions." (PMID 33884101, 2021). "In acute myocardial infarction (AMI), DRAM1 exerted cardiomyocyte protection by increasing ATG7 expression and interacting with ATG7; additionally, DRAM1 enhances the conversion of autophagosomes to autophagolysosomes." (PMID 32943616, 2020). "Following induction of myocardial infarction, we observed decreased protein expression of LC3B-II/LC3B-I and ATG7, alongside increased expression of p62, in cardiac tissues of METTL3-overexpressing mice compared to controls, indicating suppressed autophagy levels." (PMID 39893158, 2025).
myocardial infarction (continued). "We currently do not know why Atg7-C402S–KI mice exhibited more significantly enhanced myocardial infarction than Atg7-C294S–KI mice in response to myocardial ischemia." (PMID 36480290, 2023). "The differences in ATG7 expression and PGD expression did not occur until more than 48 h after myocardial infarction." (PMID 36407421, 2022).
ovarian carcinoma (23 papers, 2012 to 2026). A malignant neoplasm originating from the surface ovarian epithelium. "The OS of ovarian cancer patients prolonged with the high-expression of ATG7, G6PD, SLC3A2, MAP1LC3C and PTGS2, but shrank with the increased expression of NFS1, VDAC2, ACSL3." (PMID 35039008, 2022). "The present study also observed that miR-129 inhibited the autophagy of ovarian cancer cells by directly targeting ATG7." (PMID 33637694, 2021). "LncRNA-HULC can interact with autophagy related 7 (ATG7) proteins, serving as an oncogenic factor through inhibiting the ATG7-related pathway in ovarian cancer." (PMID 32756339, 2020). "HULC expression levels were increased in ovarian cancer by decreasing ATG7 to decrease autophagy." (PMID 37910386, 2023). "However, in ovarian cancer, ginsenoside 20(S)-Rg3 enhanced autophagy by upregulating autophagy-related molecules, including LC3-II, Atg5 and Atg7, thereby inhibiting the invasion and metastasis of ovarian cancer cells." (PMID 32934709, 2020). "It was reported that miR‐200a regulated autophagy in ovarian cancer via the ATG7 pathway." (PMID 30945454, 2019). "Taken together, our results show that HULC may promote ovarian carcinoma tumorigenesis by inhibiting ATG7 and inducing progression by regulating ITGB1." (PMID 29022892, 2017). "The objective of this study demonstrates that HULC may promote ovarian carcinoma tumorigenesis by inhibiting ATG7 and induce progression by regulating ITGB1." (PMID 29022892, 2017). "Following HULC siRNA transfection of ovarian cancer cells, ATG7, LC3 and LAMP1 mRNA and protein expression both were significantly higher than in the control, whereas expression of SQSTM1 and ITGB1 was significantly decreased by HULC siRNA transfection compared with the negative control (P<0.05)." (PMID 29022892, 2017). "DCA dramatically upregulated the mRNA level of ATG7 in ovarian cancer cells, suggesting that ATG7 may be involved in the DCA-induced protective autophagy." (PMID 27449090, 2016). "Down-regulation of ATG5 and ATG7 block autophagy induction in ovarian cancer cell lines." (PMID 27825125, 2016). "In this study, we revealed that DCA induced a protective autophagy in ovarian cancer cells, and ATG7 may play a role in this process, but the detailed mechanism needs to be further studied." (PMID 27449090, 2016). "However, suppression of autophagy at the early stage by knockdown of Atg7, as well as at the late stage by cotreatment with chroroquine or bafilomycin A1 demonstrated little effects on cytotoxicity of ovarian cancer cells mediated by proteasome inhibition." (PMID 23270461, 2012). "According to the previous study, miR‐200a could mediate ATG7 in ovarian cancer." (PMID 30945454, 2019). "Therefore, we suggest that the lncRNA HULC may cause changes in cell homeostasis by inhibiting autophagy and promoting ovarian cancer by regulating ATG7, LC3, LAMP1 and SQSTM1 expression." (PMID 29022892, 2017). "Silencing the expression of ATG7 or BECN1, two autophagy genes, rescued the migratory phenotype of the NKX3-2-silenced ovarian cancer cells." (PMID 39513923, 2024). "In epithelial ovarian cancer, CircRNA-AB11FIP1 can increase demethylase FTO level and activate autophagy by altering the m6A level of ATG7 to promote the malignant behavior of ovarian cancer cells." (PMID 36632456, 2023). "By knocking down LC3B (LC3B−) in ovarian cancer cell lines, western blot showed that compared with the control group, the expression of LC3B, Atg7 and MDR1 was decreased in the LC3B− group." (PMID 31384174, 2019). "Transfection of cells with Beclin1 siRNAs or ATG7 siRNAs blocked the accumulation of LC3-II after APG-1387 treatment, a result which indicating that APG-1387 induced the autophagy of ovarian cancer cells." (PMID 29530056, 2018). "The proposed target genes also seem quite different for different cancers, e.g. TIF1 (gastric cancer), ATG7 (hepatocarcinoma), and KLF2 (ovarian cancer)." (PMID 28418884, 2017).
ovarian carcinoma (continued). "Inhibition of autophagy by chloroquine (CQ) or silence of ATG7 dramatically enhanced the DCA-induced apoptosis and cytotoxicity, indicating that DCA induces protective autophagy in ovarian cancer cells." (PMID 27449090, 2016). "Studies convincingly showed that the expressions of ATG7-acivated ATG5-ATG12 conjugates were consistent with LC3-II and Beclin1 in ovarian cancer." (PMID 27825125, 2016). "Additionally, the MALAT1/MARCH7 Autophagy Related 7 (ATG7) feedback loop plays a critical role in promoting autophagy, migration, and invasion in ovarian cancer." (PMID 38462600, 2024). "In addition, MEnZn‐CuO NPs also showed significant upregulation of ATG7 and p‐ULK after treatment of two ovarian cancer cell lines." (PMID 37206208, 2023). "For example, circEEF2 could bind with miR-6881-3p to upregulate ATG7 and ATG5 expression, promoting the autophagy process in ovarian cancer." (PMID 36187468, 2022). "Unlike the Beclin1, efficient ATG5 and ATG7 knockdown could block autophagy induction in ovarian cancer cell lines, as evidenced by suppression of LC3-II." (PMID 27825125, 2016). "Similarly, knockdown of HOTAIR can inhibit autophagy via decreasing autophagy related 7 (ATG7) expression, and the inhibition of cisplatin-induced autophagy by silencing HOTAIR has been shown to enhance the chemotherapeutic efficacy of cisplatin in ovarian cancer." (PMID 34512721, 2021). "However, dysfunction of ATG7 does not make sense in ovarian cancer migration and invasion." (PMID 29022892, 2017).
diabetes (22 papers, 2011 to 2025). "As mentioned, we showed that loss of the critical autophagy enzyme, ATG7, leads to the development of diabetes, and at a sex dependent rate." (PMID 39944686, 2025). "When these ATG7 KO mice were crossed to ob/ob mice (a model for obesity with a mutation in the leptin gene) the progeny displayed severe diabetes suggesting that autophagic impairment in obese animals might make them more susceptible to diabetes." (PMID 29950970, 2018). "Similarly to Atg7f/f:RIP-Cre mice, Atg7+/− mice develop severe and persistent diabetes only when they are crossed with leptin-deficient (ob/ob) mice or fed a high-fat diet (HFD)." (PMID 30249977, 2018). "Autophagy is a cellular degradation-recycling system for aggregated proteins and damaged organelles, and its dysregulation characterized in Atg5 or Atg7-deifient mice is implicated in various age-related diseases including neurodegeneration, diabetes, and hepatocarcinoma." (PMID 24260490, 2013). "Moreover, in vivo models of Atg7-deficient mice, the β cell-specific Atg7 knockout mice, and the db/db mouse model have revealed the vital role of autophagy in the progression of diabetes as well as in preserving the function of pancreatic β cells." (PMID 37189396, 2023). "For example, mice with KO of Atg7, an essential autophagy gene in pancreatic β-cells producing insulin, showed structural and functional defects of pancreatic β-cells, resulting in glucose intolerance and susceptibility to diabetes in the presence of metabolic stress." (PMID 35237600, 2022). "The critical steps of Atg8 and Atg12 conjugation are directly involved in ATG7 which plays a role in the development of a transgenic animal model of diabetes." (PMID 33691614, 2021). "To investigate the therapeutic effects of HuR and Atg7 on DB‐IVDD in vivo, we established an STZ‐induced diabetic rat model and injected lentivirus into the intervertebral disc to regulate the expressions of HuR and Atg7." (PMID 33372336, 2021). "Therefore, Lim and collaborators showed that mice with global haploinsufficiency of the gene Atg7 (Atg7 (+/−) mice) develop diabetes when crossed with the ob/ob mice." (PMID 38895630, 2024). "Interestingly, haploinsufficiency in the key autophagy regulator Atg7 did not directly result in metabolic abnormalities in the absence of nutrient stress, but rather in a predisposition to diabetes in a genetic or diet-induced obesogenic context." (PMID 30249977, 2018). "To determine the effects of celecoxib on autophagy lysosome system in diabetes-induced muscle atrophy, we examined the levels of BNIP3, Beclin1, LC3 II and ATG7 in tibialis anterior." (PMID 38313305, 2024). "In the current study, we found that diabetes significantly increased autophagic activation, as evidenced by the upregulation in the expression of LC3B-II, ATG5, and ATG7 and the downregulation of P62 in the hippocampus." (PMID 31788335, 2019). "Then, the deacetylated LC3 re-localizes to cytoplasm through interaction with the diabetes- and obesity-regulated gene (DOR) and the LC3-DOR complex binds to autophagy-related protein 7 (Atg7)." (PMID 28686680, 2017). "Consequently, we studied the relationship between hepatic ATG7 mRNA and ATG7 protein expressions, and the presence of NAFLD comorbidities, such as dyslipidemia, type 2 diabetes mellitus, hypertension, and metabolic syndrome." (PMID 36674839, 2023). "Though deletion of Atg7 was not sufficient to induce diabetes,it could induce glucose intolerance,impaired insulin secretion especially when fed a high fat diet in mouse." (PMID 39996055, 2025). "Interestingly, in leptin-deficient ob/ob mice, a genetic model of obesity, the absence of Atg7 resulted in severe diabetes." (PMID 39996055, 2025).
diabetes (continued). "Interestingly however, this did not impact overall survival or PDAC-free survival in this model; suggesting that the biggest contributing factor to death due to loss of Atg7 in this model is not PDAC, but diabetes and pancreatic insufficiency." (PMID 35867735, 2022).